CCR9 (C-C motif chemokine receptor 9)
Diseases named in the same sentence as CCR9 in open-access papers (continued):
Sharing a sentence is not in itself a finding about the gene and the disease.
colitis (continued). "Collectively, these results suggest that CCR9/CCL25 interactions are not only involved in colitis pathogenesis but also correlate with colonic inflammatory burden; further supporting the existence of overlapping mucosal lymphocyte recruitment pathways between the inflamed colon and liver." (PMID 26873648, 2016). "Moreover, approximately 90% (CD4+) and 30% (CD8+) of tissue-infiltrating T-cells in colitis were identified as CCR9+ effector lymphocytes, compared to <10% of T-cells being CCR9+ in normal colon." (PMID 26873648, 2016). "In this study, we demonstrate that CCR9 deficiency in effector T cells and Tregs does not affect the development of colitis in a microbiota antigen-specific, T cell-mediated model." (PMID 26230654, 2015). "Importantly, the CCR9 antagonist Vercirnon/CCX282 reduced colonic inflammation in Crohn's disease patients with colonic involvement." (PMID 26457007, 2015). "It is our hypothesis that CCL25/CCR9 interactions promote the induction and function of iNKT cells during oxazolone-induced colitis." (PMID 24936795, 2014). "Our study suggests that CCL25/CCR9 interactions may promote the induction and function of iNKT cells during oxazolone-induced colitis." (PMID 24936795, 2014). "Interestingly, CCR9 expression on iNKT cells and the levels of iNKT cells were significantly increased during colitis." (PMID 24936795, 2014). "It is reasonable to speculate that CCL25 signaling through CCR9 might induce iNKT cells to migrate into the colon during human UC and UC-like colitis." (PMID 24936795, 2014). "In conclusion, this study has shown that CCL25/CCR9 interactions may promote the induction and function of iNKT cells during oxazolone-induced colitis." (PMID 24936795, 2014). "CCR9- or CCL25-deficient animals or antibody-mediated neutralization of these factors are needed in future studies to definitively define the function and mechanism of CCL25/CCR9 interactions in the regulation of iNKT cells during oxazolone-induced colitis." (PMID 24936795, 2014). "Indeed, CCR9 has recently been demonstrated to regulate disease development in a chemically-induced model of colitis." (PMID 23555902, 2013). "In addition, CCR9 knock-out (KO) mice with acute DSS colitis exhibit enhanced severity of clinical symptoms and tissue injury and display delayed recovery." (PMID 22162719, 2012). "The cellularity of lymphoid organs during DSS colitis was similar in WT and CCR9−/− animals." (PMID 21283540, 2011). "Like CCR9−/− animals, CCL25−/− mice were more susceptible to DSS colitis." (PMID 21283540, 2011). "In dextran sulphate sodium-induced colitis models in Kunming male mice, G. lemaneiformis inhibited CCL-25 and CCR-9 levels, increased CD40 and TGF-β1 and modulated the gut microbiota, suggesting its use as a functional food for ulcerative colitis patients." (PMID 40077614, 2025). "Therefore, here we investigate the potential role of chemokine receptor CCR9 on CD8+/Treg ratio and the effect of the recruitment of Treg subpopulations (Helios+ and Helios−) into the tumor microenvironment using the AOM/DSS induced colitis-associated colorectal cancer murine model." (PMID 40305493, 2025). "Both CCR9 and CCL25 are upregulated during DSS-induced colitis, in which the CCL25-CCR9 axis exerts a protective anti-colitic effect in the intestinal mucosa by balancing different dendritic cell subsets." (PMID 36982601, 2023). "The expression of RA-regulated gut homing molecules including α4β7 integrin, and CCR9, along with MADCAM1 were all reduced in colitis mice revealing compromised immunity due to reduced RA signaling." (PMID 35889745, 2022). "The results show that CCL25 and CCR9 are both expressed in the large intestine and are upregulated during DSS colitis." (PMID 34490243, 2021). "CCR9 expression is increased in patients with IBD and has been shown to regulate colitis development in various animal models." (PMID 26230654, 2015).
colitis (continued). "To examine the correlation between CCL25/CCR9 interactions and NKT cells, we used oxazolone-induced colitis in mice." (PMID 24936795, 2014). "Upregulated mucosal expression of numerous chemokines and their counter receptors including CXCL8 (IL-8)/CXCR2, CXCL9,10,11/CXCR3, CCL25/CCR9, CCL19,21/CCR7, and CCL20/CCR6 is evident in active IBD and in models of colitis." (PMID 22162719, 2012). "Our data show that CCL25 expression increases during DSS colitis, suggesting a regulatory role of CCL25/CCR9 interactions during large intestinal inflammation." (PMID 21283540, 2011). "We therefore compared the distribution of DC subsets in CCR9−/− and WT animals at steady state and during DSS colitis." (PMID 21283540, 2011). "Alternately, interactions between CCL25 and CCR9, known to specifically target lymphocytes to the small intestine compartment, have recently been found to regulate large intestinal immunity in a chemically-induced model of colitis, and may play a role in in vivo immunity to Trichuris." (PMID 21573179, 2011). "On achieving remission from a colitis flare, the colonic CCL25 gradient is attenuated, and primed mucosal CCR9+ lymphocytes now become permissive to recruitment to the liver sinusoids in response to aberrant hepatic endothelial CCL25 expression – as observed in the PSC liver." (PMID 26873648, 2016). "CCR9 expression on naïve T effector cells or on Treg cells is not required for induction or regulation of colitis." (PMID 26230654, 2015). "In order to test CCR9 inhibition in a nonprophylactic regimen, that is, starting treatment during the onset of colitis, 16-week-old mdr1a−/− mice were randomized to receive either CCX282-B or vehicle." (PMID 26457007, 2015). "In this study, we investigated the role of CCR9 and CCL25 in colonic inflammation." (PMID 26457007, 2015). "Importantly, we demonstrated that human UC and UC-like colitis upregulated the expression of NKT, CCL25 and CCR9 in both humans and mice." (PMID 24936795, 2014). "To determine whether colitis affects the expression levels of NK1.1, CCL25 and CCR9, we analyzed the mRNA expression levels using qPCR." (PMID 24936795, 2014). "CCL25 and CCR9 are both expressed in the large intestine and are upregulated during DSS colitis." (PMID 21283540, 2011). "Our results also suggest the concerted action of two functionally distinct pDCs subsets: a CCR9-positive tolerogenic pDC subset that regulates the inflammatory response during and after DSS colitis and a CCR9-negative predominantly inflammatory pDC subset." (PMID 21283540, 2011). "Increased IBD scores, more pronounced weight loss, a delay in recovery from acute inflammation and the inability to regain initial body weight during the experimental time period support the critical role for CCL25/CCR9 dependent trafficking events during the acute and recovery phase of DSS colitis." (PMID 21283540, 2011). "Unlike other models of murine colitis, our model shows that the absence of CCR9 does not change the immune profile of the inflammatory response." (PMID 21283540, 2011). "However, the role of CCL25/CCR9 interactions in the regulation of NKT cells during colitis has not been studied." (PMID 24936795, 2014). "The decision to include patients with large bowel disease was based on experimental evidence that CCR9 and TECK are expressed in both small and large bowel, and emerging experimental evidence that CCR9 inhibition is effective in the MDR1a−/− mouse model of colitis." (PMID 23527300, 2013). "However, prior to this study, no work has been presented on CCL25/CCR9 interactions in an experimental acute colitis mouse model mediated by DSS exposure." (PMID 21283540, 2011). "B. infantis feeding to healthy animals significantly reduced α4β7+ and CCR9+ lymphocytes within the LP, however B. infantis feeding to animals with DSS-induced colitis did not alter α4β7+ or CCR9+ lymphocyte numbers." (PMID 23704880, 2013).
colitis (continued). "Given the fact that CCR9-expressing pDCs are inducers of T regulatory cell functions, further examination of Tregs distribution and function would determine whether Tregs play a role in DSS colitis recovery and whether or not it is CCL25/CCR9 dependent." (PMID 21283540, 2011).
inflammatory bowel disease (25 papers, 2012 to 2025). A spectrum of small and large bowel inflammatory diseases of unknown etiology. "Receptor dysregulation is associated with a variety of inflammatory bowel diseases such as Crohn's and ulcerative colitis, whereas aberrant CCR9 overexpression correlates with tumor metastasis." (PMID 40154615, 2025). "The G protein-coupled chemokine receptor CCR9 plays a major role in inflammatory bowel disease and is implicated in cancer." (PMID 40825773, 2025). "The expression of CCR9 on monocytes and the CCR9/CCL25 axis have been associated with autoimmune diseases such as inflammatory bowel disease, rheumatoid arthritis (RA), and ankylosing spondylitis." (PMID 38247848, 2024). "In recent years, research has brought more evidence of how CCR9/CCL25 contributes to inflammation, which are associated with several diseases, including cardiovascular disease (CVD), hepatitis, arthritis, inflammatory bowel disease, and asthma." (PMID 39199524, 2024). "Modulation of the interaction between CCL25 and its receptor CCR9 is recognized as a therapeutic strategy against the mucosal inflammation in patients with Crohn’s disease, and in inflammatory bowel disease." (PMID 33224151, 2020). "The principal targets for anti-chemokine therapy in inflammatory bowel disease (IBD) have been the receptors CCR9 and CXCR3 and their respective ligands CCL25 and CXCL10." (PMID 30137309, 2018). "CCR9-expressing monocytes comprise a pro-inflammatory subset in inflammatory bowel disease, and also increased in arthritis patients." (PMID 25251539, 2014). "Additionally, STARD10 is linked to resilience against Paratuberculosis, STX2 against Escherichia coli, CCR9 shows potential for treating inflammatory bowel disease, and BANK1 regulates innate immune signaling in B cells." (PMID 38684985, 2024). "CD4+ T helper (Th) cells that express the gut homing chemokine receptor CCR9 are increased in the peripheral blood of patients with inflammatory bowel disease and Sjögren's syndrome and in the inflamed lesions of autoimmune diseases that affect the accessory organs of the digestive system." (PMID 30662436, 2018). "Regarding the potential clinical applications of induced Treg cells, their efficacy to treat inflammatory bowel disease may be hampered by a variable inter-individual expression of CCR9." (PMID 28746369, 2017). "CCR9 is a key regulator of colon inflammation, contributing to the pathogenesis of inflammatory bowel disease (IBD) through the recruitment of T cells into the colon mucosa." (PMID 40305493, 2025). "Due to the upregulation of CCL25 and recruitment of CCR9+ immune cells in the gut of inflammatory bowel disease (IBD) patients, CCR9 is considered as a potential therapeutic target to control gut inflammation." (PMID 33123124, 2020). "Surprisingly, although MAIT cells are found in the gut and associated with inflammatory bowel disease and colonic cancer, we detected very few cells that expressed the gut-homing integrin α4β7 or chemokine receptor CCR9, suggesting that hepatic MAIT cells are most likely not derived from the gut." (PMID 26743076, 2016). "Significant upregulation of CCR9, CCL25, and MAdCAM-1 suggests increased lymphocyte trafficking to the gut, similar to mechanisms described in human inflammatory bowel disease." (PMID 40564263, 2025). "This is the case of anti-VLA-4 neutralizing antibodies (natalizumab) for multiple sclerosis therapy and of anti-CCR9 compounds now in phase III clinical trials for treatment of Crohn’s disease and inflammatory bowel disease (IBD)." (PMID 26284069, 2015). "More recently, promising but preliminary results were reported for the CCR1 inhibitor CCX354-C in RA patients as well as the CCR9 inhibitor CCX282 in Crohn’s disease and inflammatory bowel disease." (PMID 22912856, 2012).
inflammatory bowel disease (continued). "Literature data thus far indicate that the CCR9/CCL25 axis participates in several inflammatory diseases, including cardiovascular diseases, autoimmune diseases, hepatitis, rheumatoid arthritis, inflammatory bowel disease, and asthma, but the mechanism of action still needs to be elucidated." (PMID 38612597, 2024). "The CCL25-CCR9 axis is crucial for mucosal lymphocyte recruitment to the small intestine followed by accumulating CCR9+CD4+ tissue-infiltrating T cells in both Crohn’s disease and a murine model of inflammatory bowel disease." (PMID 35744024, 2022). "Over the years, the role of CCR9/CCL25 in inflammation and related diseases has become increasingly clearness, including cardiovascular disease (CVD), hepatitis, arthritis, inflammatory bowel disease, and asthma." (PMID 34490243, 2021). "In the context of CCR9-dependent pDC distribution in mice, we successfully confirmed the upregulation of CCL25 in human small intestines from patients with Crohn’s disease, which is consistent with a previous report on the abundance of gut-tropic pDCs in patients with inflammatory bowel disease." (PMID 35943802, 2022). "A small molecular inhibitor of CCR9 lacked benefit for inflammatory bowel disease (IBD)." (PMID 29670611, 2018).
melanoma (22 papers, 2010 to 2025). A malignant, usually aggressive tumor composed of atypical, neoplastic melanocytes. "Finally, to evaluate the in vivo relevance of CCR9 as a tumor-associated immunosuppressive entity, CCR9 was stably knocked down in the melanoma patient-derived M579-A2 tumor cell culture using CCR9-specific shRNA (shCCR9) or the control non-targeting shRNA (shControl)." (PMID 25691366, 2015). "According to a possible beneficial influence of these cells in the control of cancer progression, CCR9+ T cells in the melanoma microenvironment have been demonstrated to inhibit metastasis." (PMID 41042869, 2025). "CCR7 mediates lymphocyte migration, and CCR9 is involved in rare metastases to the small intestine in melanoma." (PMID 36092920, 2022). "This is believed to be due to the high expression of the chemokine ligand CCR9 in the small bowel, therefore promoting transmigration and homing of melanoma tumour cells which are known to have significant surface expression of the chemokine receptor CCR9." (PMID 36195726, 2022). "CCL25 and its receptor C-C motif chemokine receptor 9 (CCR9) are overexpressed in cancers such as leukemia, ovarian cancer, breast cancer, prostate cancer, liver cancer, lung cancer, and melanoma." (PMID 35240026, 2022). "CCR9 was detected on circulating tumor cells of melanoma patients, along with tumor cell migration and distant metastasis." (PMID 32308544, 2020). "Unfortunately, to date, the role of CCR9 expression on immune cells in melanoma and other cancers is poorly understood." (PMID 30420855, 2018). "CCL25/CCR9 signaling enhanced invasion and metastasis in breast cancer, melanoma, and ovarian cancer." (PMID 30723697, 2018). "We have investigated the impact of CCR9 expression on the membrane of circulating T cells in stage IV melanoma patients." (PMID 30420855, 2018). "Studies have shown that CCR9 is highly expressed in melanoma skin lesions, and that melanoma cells are specifically targeted to the small intestine when CCL25/CCR9 signaling is activated." (PMID 26879872, 2016). "Recent data have shown that CCR9 is functionally and significantly expressed in various cancers, such as acute lymphocytic leukemia, melanoma, prostate cancer, pancreatic cancer, breast cancer, ovarian cancer and colon cancer." (PMID 26168791, 2015). "In a previous study we observed a strong correlation between functional CCR9 expression in melanoma and the occurrence of intestinal metastases." (PMID 22433180, 2012). "CCL25 is produced by the small bowel and thought to mediate specific interaction with CCR9 expressing melanomas." (PMID 24212610, 2010). "Other studies concluded CCR9 is highly expressed by melanoma cells and all melanoma cells isolated from small intestine metastases." (PMID 20649989, 2010). "CCR9 has been reported to promote melanoma metastasis to the small intestine." (PMID 30591657, 2018). "Collectively, these results suggest that CCR9 expression at the surface of melanoma cells may be essential for the migratory process to the gut." (PMID 30420855, 2018). "Studies investigating melanoma metastasis demonstrate that CCR9 is highly expressed in melanoma cells and small intestinal metastasis and that functional expression of CCR9 on melanoma cells mediates migration to the small intestine, explaining their preferential migration to the small intestine." (PMID 24259307, 2013). "In patients with melanoma and mice with spontaneous melanoma, higher frequencies of peripheral blood CD8+CCR9+ T cells correlated with prolonged overall survival." (PMID 41042869, 2025). "A good example is the CCR9-mediated metastasis of a subset of melanoma cells to the intestine due to the expression of CCL25 there, which is intriguing considering the normal role of CCR9:CCL25 in the recruitment of CCR9+ T cells via activation of α4β7." (PMID 37173970, 2023). "CCR9 overexpression is also possibly correlated with invasiveness in response to CCL25 in T-ALL, prostate cancer, breast cancer, and melanomas." (PMID 28380463, 2017).
melanoma (continued). "Blood samples from patients with metastatic carcinoma (MC) or melanoma (MM) were enriched for CTC and expression of CR (CXCR4, CCR6, CCR7 and CCR9) was evaluated by flow cytometry." (PMID 22433180, 2012). "This may be related to the high expression of C-C motif chemokine ligand 25 (CCL25), a ligand for the C-C chemokine receptor type 9 (CCR9), in the small intestine, which may facilitate migration of melanoma cells from the skin to the small bowel." (PMID 41311777, 2025). "Notably, the combined expression of CCR9, CCL25, CD8A, and CD8B genes in tumors positively correlated with a higher DSS probability in patients with melanoma, with a better hazard ratio (HR) and P value compared to the expression of CD8A and CD8B genes only." (PMID 41042869, 2025). "As migration of CCR9-postive lymphocytes to the small intestine relies on chemoattractive effects of CCL25 and the action of αβ integrin heterodimers, studies suggest CCR9-CCL25 also mediates melanoma metastasis to the small intestine." (PMID 24259307, 2013). "It has been shown that 86% of melanoma metastases to the small bowel express CCR9, while CCR9 was not significantly expressed in metastases to other organs." (PMID 24212610, 2010).